ZNF426 (zinc finger protein 426)
Description:
May be involved in transcriptional regulation.
Synonyms: MGC2663; K-RBP
Tractability: PROTAC: ubiquitination databases record sites on it.
Gene: Protein-coding gene on chromosome 19 (9,523,223 to 9,538,826, reverse strand). Ensembl gene ENSG00000130818.
Subcellular location: Nucleus
Subcellular location (Human Protein Atlas): Nucleoplasm
Pathways (Reactome):
Gene expression (Transcription): Generic Transcription Pathway
Gene Ontology:
Molecular function: protein binding; DNA-binding transcription factor activity, RNA polymerase II-specific; RNA polymerase II cis-regulatory region sequence-specific DNA binding
Biological process: regulation of transcription by RNA polymerase II; regulation of DNA-templated transcription
Cellular component: nucleus
Genetic constraint (gnomAD): Loss-of-function variants: 16 observed, 19.86 expected, observed/expected ratio (o/e) 0.81, 90% interval 0.54 to 1.22. The upper end of that interval is the gene's LOEUF score, 1.22, which puts it in group 5 of 6, group 1 being the genes least tolerant of losing a copy. Missense variants: 637 observed, 681 expected, observed/expected ratio (o/e) 0.94, 90% interval 0.88 to 1. Synonymous variants: 270 observed, 233.38 expected, observed/expected ratio (o/e) 1.16, 90% interval 1.05 to 1.28.
Homologues: Orthologues: chimpanzee ZNF426 (99% identical), macaque ZNF426 (95% identical), rabbit ZNF426 (77% identical), rat Zfp426 (74% identical), mouse Zfp426 (73% identical). Paralogues in human: ZNF333 (37% identical), ZNF627 (37% identical), ZKSCAN7 (36% identical), ZNF287 (36% identical), ZNF527 (36% identical), ZNF34 (35% identical), ZNF852 (35% identical), ZNF136 (34% identical), ZNF285 (34% identical), ZNF214 (33% identical), ZNF416 (33% identical), ZNF17 (32% identical), and 38 more.
Diseases named in the same sentence as ZNF426 in open-access papers:
ZNF426 is named in the same sentence as 3 diseases in open-access papers, as found by Europe PMC text mining. Sharing a sentence is not in itself a finding about the gene and the disease. The quoted sentences say what the papers report.
lung adenocarcinoma (1 paper, 2018). A carcinoma that arises from the lung and is characterized by the presence of malignant glandular epithelial cells. "Of these, 18 could be tested in the TCGA expression data for lung adenocarcinoma, and 3 met only nominal significance (logrank test p-value < 0.05): NARS (p = 0.03), an eQTL target gene in lung, as well as ZNF426 (p = 0.02), and TCEA1 (p = 0.023)." (PMID 29335598, 2018).
tumor (2 papers, 2022 to 2025). "Based on the UALCAN database, we observed a significant downregulation of ZFP28, ZNF132, ZNF418, ZNF426, ZNF540, and ZNF880 expression levels in primary tumor tissues compared to normal tissues." (PMID 36547193, 2022).
ZNF426 also shares sentences with these, for which no sentence is quoted: cancer (1 paper).